TSC2 (TSC complex subunit 2)
Diseases named in the same sentence as TSC2 in open-access papers (continued):
Sharing a sentence is not in itself a finding about the gene and the disease.
tuberous sclerosis (continued). "TSC2 acts as an important tumor suppressor gene, mutations within which are associated with the development of tuberous sclerosis and implicated in multiple tumor types." (PMID 31783925, 2019). "mTORC1 abnormal activation induced by mutations of TSC1 or TSC2 contributes to the development of the genetic disorder tuberous sclerosis complex (TSC), which is defined by benign hamartomas in several organ systems." (PMID 31088250, 2019). "SEGAs are tumors frequently arising in patients with tuberous sclerosis complex that have activated mTORC1 signaling due to mutations frequently affecting the TSC1 or TSC2 genes." (PMID 31510109, 2019). "Mutations in the tumor suppressor genes encoding TSC1 (Hamartin) and TSC2 (Tuberin) cause a multisystemic tumor syndrome termed tuberous sclerosis complex (TSC)." (PMID 29396625, 2018). "The first patient, with tuberous sclerosis attributable to a rare TSC2 (c.C5026T; p.R1676W) mutation, exhibited a prominent unilateral iris coloboma situated at 12 o'clock." (PMID 29522511, 2018). "Mutations in the TSC1 or TSC2 gene lead to the dysfunction of hamartin or tuberin proteins, which cause tuberous sclerosis complex." (PMID 30236073, 2018). "Tuberous sclerosis complex is caused by monoallelic mutations in TSC1 (about 20% of cases) or TSC2 (about 70% of cases) (Leiden open variation database)." (PMID 29552546, 2018). "Loss of function of Tuberous Sclerosis Complex 1 (TSC1) or TSC2 in the setting of the genetic condition, Tuberous Sclerosis Complex, activates mTORC1 and downregulates the basal level autophagy in dividing cells." (PMID 29540819, 2018). "Tuberous sclerosis (TSC) is an inherited disease caused by mutations in TSC1 or TSC2 that lead to aberrant activation of mTOR and development of tumours in multiple organs." (PMID 28938574, 2017). "Such mutations of TSC1 or TSC2 cause tuberous sclerosis, a multisystem disorder associated with tumor formation in the brain, heart, lung, kidney, or eye." (PMID 28445147, 2017). "TSC1 and TSC2 are tumour suppressors whose genes have been found to be mutated in the multisystemic tumour syndrome, tuberous sclerosis." (PMID 28561026, 2017). "Akt inhibits the activity of the TSC1/TSC2 (proteins harboring mutations in tuberous sclerosis) complex, a negative regulator of mammalian target of rapamaycin (mTOR), which regulates autophagy." (PMID 27911875, 2016). "Tuberous sclerosis complex is an autosomal dominant disorder caused by mutations in either the TSC1 or TSC2 gene." (PMID 27458336, 2016). "All 41 coding TSC2 exons, except exons 25 and 31, include both obviously truncating variants and fully confirmed missense variants that cause tuberous sclerosis." (PMID 26703369, 2016). "Tuberous sclerosis (TSC) is a monogenic disease resulting from defects of the TSC1 or TSC2 genes, which encode the proteins forming hamartin-tuberin tumor suppressor complex, the mammalian target of rapamycin complex (mTOR)." (PMID 27680012, 2016). "Mutation of TSC2 is responsible for the development of Tuberous Sclerosis whereas activation of TSC2 has been reported to increase autophagy of the neurons in a model of Parkinson‘s disease." (PMID 26808779, 2016). "Mutations in the tumor suppressor genes encoding TSC1 (Hamartin) and TSC2 (Tuberin) lead to a multisystemic tumor syndrome called tuberous sclerosis, which is characterized by neoplastic lesions (i.e., hamartomas)." (PMID 26877878, 2016). "The genes Tsc1 and Tsc2 got their names from a severe autosomal dominant disorder, called Tuberous sclerosis complex (TSC), resulting from mutations in one or two of these genes." (PMID 26795955, 2016). "The Drosophila Tuberous sclerosis (dTsc1 and dTsc2) is homologs of TSC1 and TSC2, which are mutated in patients with Tuberous Sclerosis complex (OMIM 191100; OMIM 191092)." (PMID 26089803, 2015).
tuberous sclerosis (continued). "Tuberous sclerosis (TSC) is a neurodevelopmental disorder that is caused by autosomal dominant mutations in the TSC1 or TSC2 tumor suppressor genes, which function as negative regulators of the mTOR signaling cascade." (PMID 26483618, 2015). "The Tsc2 protein is defective in most cases of tuberous sclerosis complex (TSC), a disease that causes neurological symptoms, and is associated with brain malformations and tumors." (PMID 26693177, 2015). "TSC2 (Tuberous sclerosis complex 2) is an important tumour suppressor gene, mutations within which are linked to the development of tuberous sclerosis and implicated in multiple tumour types." (PMID 24318044, 2014). "In brief, heterozygous mutations in the TSC1 or TSC2 gene cause tuberous sclerosis, a multisystem disorder, which is associated with autism in 20–60% of cases." (PMID 25114803, 2014). "Loss of function of TSC1 and TSC2 leads to mTOR activation in patients with tuberous sclerosis, which has been associated with pancreatic NETs." (PMID 25092520, 2014). "A clear distinction between individuals with TSC gene mutations who acquire Tuberous Sclerosis vs. S-LAM is that the somatic mutations in TSC1 or TSC2 are more widespread in those with TSC, and are typically also present in the germline." (PMID 25505789, 2014). "PMSE shares some similarities to tuberous sclerosis caused by inactivating mutations in TSC2, including cortical dysplasia, epilepsy and neurons with abnormal morphology." (PMID 24225308, 2013). "Tuberous sclerosis complex is exclusively associated with mutations in either the TSC1 or TSC2 tumour suppressor gene, which encodes the proteins hamartin and tuberin, respectively." (PMID 23143994, 2013). "TSC1 and TSC2, mutated in tuberous sclerosis, form a complex which permits the functioning of a TSC2 GTPase activating protein for Rheb GTPase which inhibits the mTOR pathway." (PMID 24155705, 2013). "About 85% of cases of tuberous sclerosis complex are caused by loss of function mutations in either TSC1 or TSC2, resulting in hyperactivation of mTORC1 in affected tissues." (PMID 24379984, 2013). "The tumor-suppressor genes TSC1 and TSC2 are mutated in tuberous sclerosis, an autosomal dominant multisystem disorder." (PMID 23355874, 2013). "In humans, mutation of either the Tsc1 or the Tsc2 gene causes tuberous sclerosis complex, a multisystem genetic disease, which is commonly characterized by neurological symptoms, such as seizures, autism, mental retardation and learning disabilities." (PMID 23143994, 2013). "Tuberous sclerosis complex (TSC) is an inherited disease caused by a heterozygous germ line mutation of either the Tsc1 or Tsc2 gene that is manifested in early childhood." (PMID 22848848, 2012). "This is precisely the situation that exists in individuals with tuberous sclerosis since heterozygosity for TSC1 or TSC2 is causative for the disorder." (PMID 22319582, 2012). "Deletion of either Tsc1 or Tsc2 genes, which are mutated in patients with Tuberous Sclerosis Complex and whose protein products are indirect downstream targets of LKB1 signaling, resulted in some of the same defects observed in Lkb1 mutant mice." (PMID 22916036, 2012). "Mutations in either the Tsc1 or the Tsc2 gene can cause the pathology of the tuberous sclerosis complex." (PMID 23105973, 2012). "The Eker rat, heterozygous for a dominantly inherited germline mutation in the Tsc2 tumour suppressor gene, is recognised as a valid model for human tuberous sclerosis complex." (PMID 23105973, 2012). "Tuberous sclerosis (TSC) related tumors are characterized by constitutively activated mTOR signaling due to mutations in TSC1 or TSC2." (PMID 21915260, 2011). "Tuberous Sclerosis is caused by mutations in the TSC1 or TSC2 gene and is often associated with autism, mental retardation and epilepsy." (PMID 20126541, 2010).
tuberous sclerosis (continued). "The two major regulators of the mTORC1 cascade, TSC1 (on chromosome 9) and TSC2 (on chromosome 16), are the genes mutated in a genetic disease called Tuberous Sclerosis Complex (TSC)." (PMID 19863783, 2009). "TSC1 and TSC2 are tumour-suppressor genes that are mutated in the tumour syndrome TSC (tuberous sclerosis complex)." (PMID 20041218, 2009). "Mutations in TSC1 or TSC2 result in tuberous sclerosis, a human syndrome characterized by formation of benign tumors, or hamartomas, and a range of neurological and behavioral anomalies, including epilepsy and autism." (PMID 17440611, 2007). "TSC2 negatively affects the mTOR pathway and has been associated with tuberous sclerosis complex, a hereditary disease characterized by hamartoma formation in various organs." (PMID 18047743, 2007). "The HERC1 target protein TSC2 has been associated with the development of the hereditary disorder tuberous sclerosis complex (TSC)." (PMID 18047743, 2007). "Tuberous sclerosis (TSC) is caused by mutations in the tumor suppressor genes TSC1 or TSC2." (PMID 40546967, 2025). "In addition, the folliculin gene (FLCN) is mutated in the context of Birt–Hogg–Dube syndrome and the TSC1 or TSC2 genes are mutated in the context of tuberous sclerosis complex." (PMID 40361453, 2025). "In a volumetric neuroimaging study of 1-year-olds with tuberous sclerosis complex, the cerebellar volume was related to neurodevelopmental severity in those with pathogenic TSC2 variants, suggesting the cerebellum diffusivity values of various white matter tracts in tuberous sclerosis complex." (PMID 39852149, 2025). "Tuberous sclerosis (TS) is a rare autosomal dominant disorder characterized by pathogenic mutations in TSC1 or TSC2 genes, leading to the formation of hamartomas and benign tumors in the CNS or outside it (e.g., fibromas, angiofibromas, angiomyolipomas, and cardiac rhabdomyomas)." (PMID 39492623, 2025). "Tuberous sclerosis complex is caused by pathogenic germline mutations of either the TSC1 or TSC2 gene, but somatic mutations were identified in both genes, and the combined effects of TSC1 and TSC2 mutations have been unknown." (PMID 36732866, 2023). "Mutations in either TSC1 or TSC2 contribute to the multisystem disorder tuberous sclerosis." (PMID 37834053, 2023). "AKT phosphorylation causes downstream inhibition of TSC1/TSC2 (Tuberous Sclerosis Complex)." (PMID 34828352, 2021). "Neurodevelopmental delays along with cognitive impairments are thought to stem from synaptic structure and function aberrations that are characteristic of ASDs and monogenic IDs such as FXS, RTT, tuberous sclerosis (TSC caused by mutations in the TSC1/TSC2 complex)." (PMID 34566717, 2021). "Inactivating mutations in either TSC1 or TSC2 in the germ line cause Tuberous Sclerosis Complex, an autosomal dominant neurocutaneous disorder, characterized by skin lesions, neuropsychiatric disorders and mainly benign tumors of the brain, kidney, lung, heart, and skin." (PMID 33891611, 2021). "TSC2 mutations are highly correlated with tuberous sclerosis." (PMID 33307091, 2021). "Since a decrease in melanocyte numbers and melanosome maturation hasbeen reported in ash-leaf macules of tuberous sclerosis patients harboringloss-of-function variants in TSC1 or TSC2, which encode upstream inhibitors of mTOR, westudied melanogenesis in patients with MTOR-related HI." (PMID 33833411, 2021). "TSC2 is a tumor suppressor, and mutations in TSC2 can lead to tuberous sclerosis complex." (PMID 33929972, 2021). "Both patients with variants in TSC2 were diagnosed with tuberous sclerosis clinically." (PMID 32477112, 2020).
tuberous sclerosis (continued). "All patients in our study underwent TSC1/2 gene test, four patients had mutations in pathogenic TSC1 or TSC2 genes, five patients met the clinical or genetic diagnostic criteria for tuberous sclerosis, accounting for 35.7% (5/14) of EAML patients diagnosed in our hospital during the same period." (PMID 33575217, 2020). "Autosomal dominant polycystic kidney disease is defined as an inherited disorder characterized by renal cyst formation due to mutations in the PKD1 or PKD2 gene, whereas tuberous sclerosis complex is an autosomal dominant neurocutaneous syndrome caused by mutation or deletion of the TSC2 gene." (PMID 31870441, 2019). "Mutations in TSC1 and TSC2 are known to cause Tuberous Sclerosis (TSC)." (PMID 31245336, 2019). "Additionally, some genetic epilepsies are at high risk of ASD, such as tuberous sclerosis/TSC2 gene and Fragile X syndrome/FMR1 gene." (PMID 29558884, 2018). "TSC1/TSC2 variants were found in 60% patients with tuberous sclerosis complex patients." (PMID 30185235, 2018). "The novel c.3610G > A TSC2 mutation was identified in association with tuberous sclerosis complex." (PMID 30236073, 2018). "TSC1/TSC2 variants were found in 60% of patients with tuberous sclerosis complex." (PMID 30185235, 2018). "Heterozygous, loss‐of function, pathogenic variants in TSC2 cause Tuberous Sclerosis Complex (TSC)." (PMID 29271092, 2018). "Conditional deletion of the GTPase-activating protein (GAP) tuberin (Tsc2), which is mutated in the genetic disorder tuberous sclerosis, leads to neuronal migration defects in the cortex, hippocampus and cerebellum that are reminiscent of but not identical with the reeler phenotype." (PMID 27445693, 2016). "However, evidence for a tightly balanced control over synaptic translation has been provided: mutations in the gene tsc2 cause tuberous sclerosis, a disease phenotypically similar to fragile X syndrome (FXS)." (PMID 25392983, 2014). "Both TSC1 and TSC2 are tumor suppressors and are mutated in tuberous sclerosis (TSC)." (PMID 28548055, 2013). "Mutations to the TSC1 and TSC2 genes cause the disease tuberous sclerosis complex." (PMID 23006675, 2012). "In addition, increased USVs in newborn pups was also reported in mice of BTBR T+tf/J, tuberous sclerosis gene Tsc2 mutation, and paternal duplication of human 15q11–q13 region." (PMID 20808828, 2010). "Tuberous sclerosis complex (TSC) is an autosomal dominant disorder caused by mutations in TSC1 or TSC2, characterized in the kidney by angiomyolipoma (AML), renal cysts, and, less frequently, renal cell carcinoma, which together contribute to the risk of CKD." (PMID 41302105, 2025). "Background and Clinical Significance: Tuberous sclerosis complex (TSC) is an autosomal dominant disorder caused by pathogenic variants in TSC1 or TSC2." (PMID 40722560, 2025). "Moreover, the report of PIL associated with tuberous sclerosis of Bourneville with TSC2-gene mutation in a 2-year-old child described a favorable evolution with sirolimus progressively increased to 0.61 mg/kg and plasma levels reaching 10.7 ng/mL (reference level: 3.0–18.0 ng/mL)." (PMID 40640921, 2025). "The International TSC Clinical Consensus Group has recommended that independent genetic identification of pathogenic variants of the TSC1 or TSC2 gene should be sufficient to diagnose tuberous sclerosis disease regardless of clinical data." (PMID 39410026, 2024). "At the same time, loss-of-function mutations in either Tsc1 or Tsc2 genes, which are direct intracellular inhibitors of mTORC1, cause a genetic disorder named Tuberous Sclerosis Complex (TSC), characterized by the growth of benign tumors in multiple areas." (PMID 38531868, 2024). "Mutations of TSC1 and TSC2 genes cause classical Tuberous Sclerosis Complex (TSC), a neurocutaneous disorder characterized by a tendency to develop hamartias, hamartomas, and other tumors." (PMID 37063680, 2023).
tuberous sclerosis (continued). "Tuberous sclerosis (TSC) has been reported to be an inheritable disease resulting from mutations in either the TSC complex subunit 1 (TSC1) or 2 (TSC2) genes." (PMID 36539038, 2023). "Tuberous Sclerosis Complex (TSC) is a syndrome caused by mutations in either the Tsc1 or Tsc2 genes." (PMID 38201256, 2023). "Loss-of-function mutations in TSC1 or TSC2 can give rise to an autosomal dominant disorder of tuberous sclerosis complex (TSC) that invades multiple organs, such as brain, skin, heart, lungs, and kidneys." (PMID 37251941, 2023). "One of these cases was diagnosed as tuberous sclerosis complex (TSC) due to the combination of cutaneous findings and a TSC2 gene mutation, with multiple cortical tubers and subependymal nodules present." (PMID 40217366, 2023). "Tuberous Sclerosis Complex (TSC) is an autosomal dominant disorder that results in the loss of either the Tsc1 or Tsc2 gene." (PMID 38268565, 2023). "TSC2 is a tumor suppressor gene as well as a disease-causing gene for autosomal dominant disorder tuberous sclerosis complex (TSC)." (PMID 37251941, 2023). "The other highly ASD-penetrant heterozygous mutations in the TSC1 or TSC2 genes, key regulators of mTOR signaling, cause tuberous sclerosis (TSC)." (PMID 35055151, 2022). "This drug is beneficial for the treatment of seizures in animal models of genetic mTOR hyperactivation and in patients with tuberous sclerosis complex (TSC) caused by TSC2 or TSC1 mutation leading to mTOR hyperactivation." (PMID 35040598, 2022). "Tuberous sclerosis complex (TSC) is an autosomal dominant disease caused by inactivating mutations in TSC1 or TSC2.Patients with TSC often require organ transplantation after organ failure." (PMID 36186130, 2022). "Tuberous sclerosis complex (TSC) is caused by mutations in the Tsc1 or Tsc2 genes, whose products form a complex and inactivate the small G-protein Rheb1." (PMID 36606143, 2022). "Hyperactive mTORC1 signaling is a clinical feature of patients with tuberous sclerosis complex (TSC) which is caused by inactivating pathogenic variants in either TSC1 or TSC2 genes, and sclerotic bone lesions have been frequently reported in TSC patients." (PMID 36060812, 2022). "Tuberous sclerosis (TSC) is a multisystem autosomal dominant genetic disorder due to loss of function of TSC1/TSC2 resulting in increased mTOR (mammalian target of rapamycin) signaling." (PMID 32973442, 2020). "In this report, we describe a case of severe TSC diagnosed in utero and associated with a specific mutation in the gene tuberous sclerosis complex 2 (TSC2)." (PMID 32873234, 2020). "Tuberous sclerosis complex (TSC) is characterized by a mutation in either the TSC1 or TSC2 genes; approximately 50% of patients with TSC have ASD." (PMID 33396736, 2020). "Intriguingly, hyperactivation of the mTORC1 pathway, is a hallmark of Tuberous Sclerosis (TSC) in patients as well Tsc1 or Tsc2 knockout mouse models, that present with a range of neurological disorders including epilepsy, relevant to NCL pathology." (PMID 31655107, 2020). "One of the neurogenetic disorders that are associated with seizures and autistic behaviors is tuberous sclerosis complex (TSC) caused by mutations in TSC1 or TSC2." (PMID 30683131, 2019). "Tuberous sclerosis (TSC) is an inherited tumour syndrome caused by mutations in TSC1 or TSC2 that lead to aberrant activation of mTOR." (PMID 28938574, 2017). "Mutations in either the tsc1 or the tsc2 genes cause the hamartomatous syndrome tuberous sclerosis complex (TSC)." (PMID 26536660, 2015). "Mutations in TSC1 or TSC2 cause the human genetic disease Tuberous Sclerosis Complex (TSC), and studies in both mouse models and human TSC-related tumors demonstrated that mTORC1 was highly activated in these tumors." (PMID 26137524, 2015).